HMGB1 (high mobility group box 1)
Diseases named in the same sentence as HMGB1 in open-access papers (continued):
Sharing a sentence is not in itself a finding about the gene and the disease.
infection (continued). "HMGB1 localized in the nucleus in resting cells, whereas PAO1 infection decreased its nuclear levels but increased cytosolic levels." (PMID 24923305, 2014). "We showed that Pseudomonas PAO1 strain infection facilitated autophagosome formation, whereas knockdown of FIP200 inhibited autophagosome formation and HMGB1 expression in MH-S cells." (PMID 24923305, 2014). "HMGB1 serves as an endogenous ligand of both TLR2 and TLR4, and mediates the response to infection, injury and inflammation." (PMID 22808256, 2012). "In our study, we demonstrated that stimuli that mimic infection (LPS, SEB or PMA) or pro-inflammatory mediators, as TNF-α or IL-2 or IL-15, induce the cell surface expression of HMGB1 and its secretion at 48 h or 14 days after treatment, respectively." (PMID 21915243, 2011). "Although the studies are heterogeneous in design and population size, a common finding is that patients with infection and/or SIRS have elevated levels of serum HMGB1 as compared with healthy control individuals." (PMID 18577209, 2008). "Levels of all studied inflammatory markers (HMGB1, LBP, PCT, IL-6) and infection markers (C-reactive protein, white blood cell count, neutrophils) were elevated among bacteraemic patients." (PMID 17625012, 2007). "HMGB1 was secreted only upon infection of human corneal epithelial cells, not from other cell types, and only upon infection by HAdV-D types associated with EKC." (PMID 40367285, 2025). "However, treatment with Grapiprant led to a notable reduction in the mRNA expression levels of HMGB-1 and HABP-2 at 4 and 6 h post-infection (p < 0.0001)." (PMID 40666730, 2025). "HMGB1 is releasedby cells during stress, injury, or death (especially during necrosis).When released extracellularly, it acts as a DAMP, signaling the immunesystem that there is damage or infection." (PMID 39739571, 2025). "High mobility group box 1 (HMGB1), a non-canonical mediator secreted during infection or tissue trauma, is also subject to vagal regulation in the resolution stages of inflammation." (PMID 40948785, 2025). "Similar to the findings in HFFs, we observed decreased levels of HMGB1 in all cell lines at late times post-infection (data not shown)." (PMID 39611842, 2025). "As shown, HMGB1 remains in the nucleus in the absence of infection, but has translocated to the cytoplasm by 12 hpi (inset ii)." (PMID 40367285, 2025). "In a previous work we demonstrated that children who present febrile symptoms without apparent infection have elevated concentrations of HMGB1 and S100A8 proteins (unpublished data)." (PMID 40868835, 2025). "During infection and inflammation, macrophages are exposed to a panoply of endogenous TLR ligands, including serum amyloid A (SAA), myeloid-related protein 8 (MRP8), and high-mobility group box 1 (HMGB1)." (PMID 38426494, 2024). "Research indicates that activated platelets can induce the formation of neutrophil extracellular traps (NETs) even in the absence of infection, potentially presenting high mobility group box 1 (HMGB1) to neutrophils to facilitate this process." (PMID 39022737, 2024). "Conversely, in the spinal cord tissue, a slight, but significant increase in MFI was observed for HMGB-1 only in neurons in the EAE group without infection." (PMID 38965360, 2024). "The abundance of HMGB1, a proinflammatory cytokine that promotes the recruitment of immune cells to sites of injury or infection, was not different among groups in the jejunum, ileum, and colon." (PMID 37841323, 2023). "We found that in the absence of infection, all HMGB1 constructs are soluble (compare lanes 3 and 5)." (PMID 37703278, 2023). "We observed that there is some B-box in the insoluble fraction upon infection but becomes completely soluble upon addition of the C-terminal tail, similar to full-length HMGB1 in the absence of protein VII." (PMID 37703278, 2023).
infection (continued). "The early phase of HMGB1 release at 6 h post-infection, which is cell death-independent but MLKL dependent, promotes the late phase of HMGB1 release via the activation of RAGE, initiation of a second wave of RIPK1/RIPK3/MLKL phosphorylation and occurs with cell necroptosis." (PMID 37798799, 2023). "The IL-33 concentrations were significantly higher in CF subjects than in non-CF subjects, while the HMGB1 concentrations were higher in non-CF controls with repeated infections." (PMID 36675299, 2023). "Unlike the diffuse production of HMGB1, IL-33 is basically produced in epithelial cells and has a role in tissue inflammation correlated to pathogen infection." (PMID 36675299, 2023). "Much like WT HMGB1, during mock infection mutHMGB1 is not visible within the nucleus of pre-extracted cells but remains bound to the chromatin in infected cells." (PMID 37703278, 2023). "In light of these studies, it will be fascinating to uncover the mechanisms by which HMGB1 functions not just in extracellular signaling as a response to infection but also as a target for hijacking within the nucleus to subvert host defenses." (PMID 37703278, 2023). "Studies have reported the role of RAGE in HMGB1‐induced inflammation, regeneration and autophagy and reported that TLR4 recognizes several danger signals, including HMGB1, to activate the innate immune system to prevent infection and injury." (PMID 34953035, 2022). "We initially tested the impact of the nonspecific RAGE/HMGB1 signaling inhibitor ethyl pyruvate on host survival following a uniformly lethal infection with SARS-CoV-2 (1 × 104 TCID50)." (PMID 35076028, 2022). "After infection, nonoxid-HMGB1 was added to the cultured neurons and remained present until fixation after 24 h." (PMID 35479959, 2022). "In these mice, GLY significantly reduced TLR4, but not HMGB1 or RAGE mRNA expression levels after infection." (PMID 36422579, 2022). "To further explore whether ORFV NA1/11 infection induced cell death triggered ICD, we analyzed the relative protein levels of cytoplasmic HMGB1 in A549 and LLC cells following infection with ORFV NA1/11 for 24 and 48 hours by Western blot assays." (PMID 35959371, 2022). "FPS-ZM1 treatment reduced baseline levels of HMGB1 in the lungs but did not alter the trajectory of increased HMGB1 levels as infection progressed." (PMID 35076028, 2022). "It was reported that GLY treatment effectively reduced HMGB1 expression at both mRNA and protein level in infection or non-infection corneal injury and thus to improve corneal repair." (PMID 35586052, 2022). "Furthermore, the engagement of RAGE with HMGB1 might also induce chemotaxis and the migration of monocytes, dendritic cells and neutrophils, thereby facilitating the recruitment of innate immune cells to site of the infection to orchestrate inflammatory responses." (PMID 34571869, 2021). "After a burn without infection, serum HMGB1 levels rose significantly to 50 ng/ml within minutes of the burn and returned to baseline levels within 9 h." (PMID 34152806, 2021). "Here, we found HMGB2, a paralog of HMGB1, to be upregulated at 7 DPC in Afg09 infection." (PMID 34615921, 2021). "Knockdown of HMGB1 expression was confirmed by Western blot analyses, which contributed to the upregulation of mRNA level of the granulocytic differentiation markers (CD11b, MPO, and CSF3R) as compared with the lenti-ctrl infection." (PMID 33128580, 2021). "Currently, no data are available on placental expression of proinflammatory HMGB1, oxidative damage marker 8-OHdG, and senescence marker telomere length in spontaneous preterm birth in the absence of infection." (PMID 34258068, 2021). "The first study showed that neonatal mice deficient in RAGE manifested a reduced type 1 and type 2 IFN response, blunted peripheral DC (pDC) recruitment, higher levels of HMGB1 and higher amounts of airway smooth muscle mass compared to WT mice in response to PVM infection." (PMID 32397226, 2020).
infection (continued). "Since infection is not usually present in healthy term labour, endogenous DAMPs including HMGB1, cell‐free DNA and oxysterols released from senescent cells in fetal membranes and placenta are implicated in TLR4 signalling in term labour." (PMID 32313651, 2020). "Extracellular HMGB1 may act as a pro-inflammatory mediator, stimulating the release of TNF-α during infection or sterile tissue injury, as well as by promoting migration of monocytes, DCs, and neutrophils to sites of tissue injury/inflammation." (PMID 32664328, 2020). "The intracellular accumulation of HMGB1 after dl922-947 infection was confirmed by the lack of intracellular positivity in the absence of brefeldin A (data not shown)." (PMID 31355131, 2019). "We analyzed HMGB1 levels in AF obtained from women with signs or symptoms of preterm birth who had amniocentesis to rule out infection (n = 38) or for either genetic indication (n = 10)." (PMID 31875024, 2019). "The release of HMGB1 also increases the expression of ICAM-1, VCAM-1 and pro-inflammatory cytokines in endothelial cells, suggesting a propagation of the immune response during infection or injury by HMGB149." (PMID 31748599, 2019). "High-mobility group box 1 (HMGB1) is a nuclear DNA-binding protein and released to the outside from macrophages, NK cells, dendritic cells, necrotic cells, and apoptotic cells according to infection, injury, and inflammation." (PMID 31766574, 2019). "In conclusion, HMGB1 mRNA transcription was not activated by the infection of the gnotobiotic piglets with S. Typhimurium within 24 hrs." (PMID 31847111, 2019). "Based on the supernatant screening, we found that both NIH-3T3 and 3T6 Swiss albino cells secreted ATP and HMGB1 following infection with replication-competent HSV1716gfp, but neither were detectable with UV-inactivated HSV1716gfp." (PMID 29543735, 2018). "Together, these data demonstrate that in the absence of RAGE, PVM infection increases ASM mass in an HMGB1 dependent manner." (PMID 28099113, 2017). "In terms of the expression of HGBM1, it was significantly reduced by Mut-1 infection, while WT and Mut-2 infections did not influence the nuclear abundance of HMGB1." (PMID 29207503, 2017). "The results showed that UV-PEDV infection also induced the release of acetylation HMGB1 in MOI-dependent manner, suggesting the involvement of virion proteins or genomic RNA in modulating HMGB1 acetylation and release." (PMID 27634894, 2016). "The expression of HMGB1 and RAGE was only tended to increase with infections for 6 h." (PMID 27667993, 2016). "Our results showed that HMGB1 levels are increased in patients with CCHFV, DOBV or PUUV infection." (PMID 27348219, 2016). "This could explain why an anti-HMGB-1 agent and/or an anti-TNF-α treatment become less effective as the infection proceeds." (PMID 27556404, 2016). "On the contrary, ΔYopM/YopM rescue strain infection triggered increased HMGB1 release without inducing caspase-1 cleavage and IL-1β secretion." (PMID 27929533, 2016). "After KEI 1025 infection, GLY treatment reduced HMGB1 (mRNA and protein levels) and improved disease outcome with significant reduction in mRNA levels of IL-1β, TLR4, CXCL2, and IL-12; protein expression (IL-1β, CXCL2); neutrophil infiltrate; and bacterial load." (PMID 27792814, 2016). "It was not until 1999 that the cytosolic HMGB-1 was found to be a proinflammatory mediator and can be secreted by activated macrophages in the context of infection, injury, or other inflammatory status." (PMID 27738641, 2016). "It was similar, but less effective when used after infection with a cytotoxic strain, which did not reduce HMGB1." (PMID 27792814, 2016). "The “all-thiol” HMGB1 binds to other chemokines (e.g., CXCL12) and stimulates leukocyte recruitment via the CXCR4 receptor or other signaling molecules to the infection or injury sites." (PMID 26257917, 2015).
infection (continued). "Importantly, FIP200 silencing significantly reduced the acetylation of HMGB1 and inhibited HMGB1 translocation in MH-S cells upon PAO1 infection." (PMID 24923305, 2014). "High mobility group box 1 (HMGB1) is a DNA binding, nuclear and cytosolic protein; in the extracellular environment, HMGB1 is an important mediator of inflammation that regulates tissue response to infection and injury." (PMID 24959003, 2014). "Serum HMGB1 levels in patients with infection (8.9 ± 2.47 ng/mL) were significantly higher than those in patients without infection (4.9 ± 1.04 ng/mL)." (PMID 25926862, 2014). "We identified that the concentration of serum HMGB1 was higher in patients with SAP than in normal healthy subjects, and it can be used as an important indicator to determine the intestinal barrier dysfunction and infection in clinical setting." (PMID 25926862, 2014). "HMGB1 increase by fetal membrane cells in response to either oxidative stress or infection can provide a positive feedback loop generating non-infectious inflammatory activation." (PMID 25469638, 2014). "HMGB1 activity is an important regulator of the fetal inflammatory response regardless of infection." (PMID 25469638, 2014). "HMGB1 is detectable by western blot in the supernatant of infected cells 4 and 6 hours post infection but not in the supernatant of uninfected cells after 6 hours." (PMID 23844129, 2013). "Although HMGB1 was highly present at the primary site of infection during S. aureus pneumonia, anti-HMGB1 treatment did not influence bacterial loads at any time point." (PMID 24342460, 2013). "Anti-HMGB1 did not influence neutrophil counts in BAL fluid at any time after infection with S. aureus." (PMID 24342460, 2013). "As observed with CBA analysis, anti-HMGB1 mAb treatment used in this study did not affect IFN-γ release induced during PbA infection, as levels were comparable to plasma IFN-γ levels in PbA-infected isotype controls." (PMID 23506269, 2013). "Anti-HMGB1 attenuated lung pathology and protein leak and reduced interleukin-1β release 6 hours after infection, but not at later time points." (PMID 24342460, 2013). "Together these data indicate that RAGE impairs clearance of S. aureus in the bronchoalveolar compartment early after infection and that HMGB1 has no role herein." (PMID 24342460, 2013). "On assessing which putative ligands of RAGE were concomitantly expressed in infection, we found that HMGB1 was not increased either at the level of gene or protein expression." (PMID 21423669, 2011). "During an infection or sterile injury, pathogens and damaged host cells release danger signals such as lipopolysaccharides (LPS), peptidoglycans (PGN), high-mobility group protein-1 (HMGB1), and double stranded DNA (dsDNA) into circulation." (PMID 21611132, 2011). "However, the average concentrations of HMGB1 in HAdV-C5-infected HFFs and in A549-infected cells (data not shown) were increased at early times post-infection but greatly reduced at the latest time points examined." (PMID 39611842, 2025). "Additionally, HMGB1 may inhibit the signaling mediated by STAT3, thus promoting autophagy and providing protection against infection in intestinal epithelial cells." (PMID 39008169, 2024). "A large body of evidence indicates that HMGB1 is also required for the development or progression of inflammation, even in the absence of infection, such as autoimmune arthritis, sterile hepatic necrosis, and other conditions that lead to inflammation and tissue injury." (PMID 35547731, 2022). "In most patients, we found increasing HMGB1 levels when comparing start to end of treatment, with undulating concentrations during therapy, which might potentially reflect not only ICD levels but also diverse confounders such as inflammation and infection." (PMID 34671818, 2022). "However, HMGB-1 expression in bovine endometrial explants was not influenced by DP1 receptor agonists or antagonists after infection." (PMID 36435808, 2022).
infection (continued). "The lack of HMGB1 expression may be due to the nature of this animal model not being a severe infection as these animals recovered." (PMID 34615921, 2021). "This factor impairs plasmacytoid dendritic cell recruitment by reducing interferon (IFN)-1 levels at the site of infection and destabilizes DNA via the host protein HMGB1 (high mobility group box 1), which may decrease IFN-1 levels at the site of infection (1 levels at the site of infection." (PMID 34956108, 2021). "We screened serum HMGB1 levels postburn, without and with infection." (PMID 34152806, 2021). "It is noteworthy that LPS is not the only partner of HMGB1 during infection or sterile injury." (PMID 33854044, 2021). "Additionally, the infection of lung cancer cells with NDV could increase the levels of ATP, HSP70/90, and HMGB1 in cell supernatant." (PMID 31217023, 2019). "Notably, whereas AdWT infection blocked NLRP3 inflammasome activity compared to uninfected cells, infection with a replication defective AdEasy vector appeared to potentiate the release of IL-1ß and HMGB1 compared to uninfected cells." (PMID 31849970, 2019). "HMGB1 is non-histone DNA-binding nuclear protein with cytokine-like activity, having both intracellular as well as extracellular activities, and is shown to be involved in many pathological processes like injury, infection, inflammation, and many diseases." (PMID 31336567, 2019). "To test this hypothesis, we screened supernatants from infected cell cultures 24 h post-HSV1716gfp infection (MOI 3) for candidate molecules including adenosine triphosphate (ATP), HMGB1, type 1 interferon (IFN-⍺, IFN-β), interleukin 1-β (IL-1β), and oncostatin M." (PMID 29543735, 2018). "Because HSV1716gfp is able to infect 3T6 Swiss albino cells, we wanted to test whether or not altering the activity of HMGB1 using the small molecule HMGB1 inhibitor glycyrrhizin would impact HSV1716gfp infection." (PMID 29543735, 2018). "In contrast to the primary infection in neonatal mice, we did not observe an increase in eosinophil numbers (Supplement 2a) or HMGB1 expression in these mice (Supplement 2b), suggesting that the predisposition of IPS-1−/− mice to virus-induced type-2 inflammation is age-dependent." (PMID 28539639, 2017). "A comparison of the peak level of HMGB-1 to the peak level of TNF-α reveals that the peak level of HMGB-1 is higher and that the time required to reach maximum concentrations of TNF-α was less than the time required for HMGB-1 (average of 9 hrs versus 24 hrs post infection)." (PMID 27556404, 2016). "We also found GLY treatment did not reduce HMGB1 levels after infection with the cytotoxic strain." (PMID 27792814, 2016). "The HMGB1 levels were higher in patients with infection during the clinical course, the HMGB1 levels in non-survivors were higher than those in survivors, and positively correlated with DAO activity, L/M ratio, the concentration of endotoxin (R = 0.484, P <0.01)." (PMID 25926862, 2014). "Whereas HMGB1 constantly shuttles between the nucleus and cytoplasm of HSV-2-uninfected cells, it gradually concentrated in the nucleus and co-purified with chromatin during the pro-apoptotic phase of the infection that occurred from 24 to 48 hours post-infection in HEC-1 cells." (PMID 21283827, 2011). "However, infection with H37Rv also gave rise to increased permeability of the plasma membrane as well as increased release of the inflammatory mediator HMGB1, indicating that the main pathway of cell death was not apoptosis." (PMID 21637850, 2011). "Furthermore, treatment of the hMDMs with YVAD or CA-074Me did not affect infection-induced HMGB1 release." (PMID 21637850, 2011). "We found that infection with H37Rv at MOI 10, but not MOI 1, over two days led to extensive DNA fragmentation, loss of mitochondrial membrane potential, loss of plasma membrane integrity, and HMGB1 release." (PMID 21637850, 2011).